IL6R (interleukin 6 receptor)
Diseases named in the same sentence as IL6R in open-access papers (continued):
Sharing a sentence is not in itself a finding about the gene and the disease.
cancer (continued). "To explore similar mechanisms in other cancers, we conducted a correlation analysis of CD59 with macrophage, IL10, IL10RB, IL6, and IL6R on KIRC, CESC, GBM, HNSC, and STAD." (PMID 39518137, 2024). "Overexpressed MCT-1 stimulates the IL-6/IL-6R/gp130/STAT3 axis, which promotes epithelial-to-mesenchymal transition and cancer stemness." (PMID 38505617, 2024). "It was also detected that HIC1 expression was positively related to several immunestimulators in different cancers, such as CXCL12 and TNFRSF4, and was negatively connected with IL-6R in TGCT." (PMID 37388742, 2023). "High fold change correlation for IL6R, TNFSF10, and BLNK DEGs was found between the matching samples and all CRC tissue samples in cancer vs. control correlation." (PMID 37869102, 2023). "Expression of adhesion molecule ICAM1 also predicts poor prognosis for several cancer types, closely mimicking the effects observed for the IL1R1 and IL6R genes." (PMID 37006265, 2023). "There was a correlation between RNA-seq and validation cohort for the IL6R, BLNK, and TNFSF10 DEGs when cancer and control tissues were compared." (PMID 37869102, 2023). "IL6R was also identified in the third-most significant KEGG pathway, ‘pathways in cancer’ (hsa05200)." (PMID 35268532, 2022). "Second, the monoclonal antibody Tocilizumab, already used in clinic to inhibit IL-6R, prevented STAT3 activation in cancer cells." (PMID 34440697, 2021). "The overall survival analysis was performed stratifying the cancer samples of each TCGA cohort based on the expression mean value of IL6, IL6R, and IL6ST by using UCSC Xena tool." (PMID 34576335, 2021). "The importance of the IL-6R/JAK/STAT3 signalling pathway for tumourigenesis is evident, as it is estimated to be aberrantly activated in >70% of human cancers." (PMID 32731620, 2020). "The MCT-1/miR-34a/IL-6/IL-6R signaling axis was revealed to promote EMT and cancer stemness in triple-negative breast cancer." (PMID 32268506, 2020). "As one of the most significantly changed cytokines, IL6R caught our attention, since it has been reported that IL-6/IL-6R complex plays a pivotal role in the JAK-STAT pathway during immune responses and cancer progression." (PMID 31903134, 2020). "miR-21 has been previously shown to regulate the expression of IL6R and PTEN in the context of human cancer cells." (PMID 32340146, 2020). "However, glycosylation profile of IL-6R in both cancer and RA is unknown." (PMID 32435655, 2020). "Collectively, oncogenic MCT-1 activation stimulates the IL-6/IL-6R/Stat3 axis that enhances EMT progression, cancer stemness and M2 polarization in the TNBC system." (PMID 30885232, 2019). "Given its critical contributions to cancer progression, IL-6 signaling pathway (IL6-/IL6R/JAK/STAT3) is being actively pursued for novel cancer therapies." (PMID 32039001, 2019). "Herein, we show that MH-mediated inhibition of p-STAT3 in breast (MDA-MB-231) and lung (A549) cancer cell lines is accompanied by decreased levels of gp130 and p-JAK2, two upstream components of the IL-6 receptor (IL-6R) signaling pathway." (PMID 31491838, 2019). "The IL-6/IL-6R/JAK/STAT3 is one of these pathways, which contributes to the development and progression of HNC cancers." (PMID 29951282, 2018). "In addition, ADAM-17 has been shown to cleave the interleukin-6 receptor (IL-6R) resulting in the shedding of soluble interleukin-6 (sIL-6) which is a prerequisite for the pathogenesis of interleukin 6 (IL-6) trans-signaling effecting multiple cellular functions related to cancer and inflammation." (PMID 29393911, 2018). "The IL6R/gp130/STAT3 signal pathway regulates CSC renewal and cancer metastasis which leads to radiotherapy resistance." (PMID 29770167, 2018). "ADAM substrates include many cancer-related proteins, such as Notch receptors and their ligands, epidermal growth factor receptor (EGFR) ligands, interleukin-6 receptor (IL-6R), tumor necrosis factor (TNF) and its receptors, E-cadherin, and CD44." (PMID 28148288, 2017).
cancer (continued). "In the present study, the smoking-related methylation changes to RUNX3, IL6R, PTAFR, and ANKRD11 (cardiovascular-related genes) and CEP135 and CDH23 (cancer-related genes) corresponded to increased gene expression." (PMID 26756918, 2016). "In the high IL-6 expression group, IL-6 receptor (IL-6R), phospho-signal tranducer and activator of transcription 3 (p-STAT3) were also detected in almost all the cancer cells." (PMID 25761055, 2015). "It is also noteworthy that, compared to ASCs-CM, hUCESCs-CM contain lower levels of factors known to participate in cancer progression, such as EGFR, FGF 4 and 9, ICAM3, IL6, IL6R, MCP3 (CCL7), MIF, sgp130 and VEGFD." (PMID 25296979, 2014). "The involvement of the JAK-STATs signaling pathway in IL-6/IL-6R signaling and involvement of STAT3 phosphorylation in EMT of cancer cells has been proved by lots of results." (PMID 24789104, 2014). "While JAK2 mutation is a common means to stimulate oncogenic STAT activity, perturbations in other signaling networks, such as those mediated by EGFR, IL-6/IL-6R or FLT3, can also contribute to activated STAT signaling in cancer cells." (PMID 21533169, 2011). "Notably, studies have shown that neutralizing IL6 or IL6R antibodies can reduce CAF-induced expression of HK2, emphasizing the important role of IL6 in promoting cancer cell growth." (PMID 40427188, 2025). "Given the known role of the IL-6/STAT3 pathway in enhancing cancer cell stemness, it was of interest to explore whether CD109-mediated IL6Rα/STAT3 pathway activation leads to increased stemness." (PMID 40317079, 2025). "Administration of SC144, a complexed IL-6R-gp130 inhibitor, alleviated mechanical and thermal hypersensitivity in BCP rats, reversing the upregulation of TRPA1, p-p38-MAPK, p-JNK, and PI3K-mTOR induced by cancer." (PMID 38940936, 2024). "Also, in most of the cancers, there was a significant correlation between UBE2C gene expression and C10orf54, CXCL12, IL6R, MICB, PVR, THEM173, and TNFSF13." (PMID 38577722, 2024). "Conversely, IL6R and MYC KO cells displayed a significant reduction in both number and size of spheres compared to SC cells (IL6R KO, p ≤ 0.001; MYC KO, p ≤ 0.01), suggesting reduced cancer malignancy." (PMID 38607055, 2024). "Overall, these studies highlight the critical roles of IL6 and IL6R, as well as CD46 and JAG1, in the survival and invasive capacity of cancer cells, and their broad promise as targets for antitumor therapies, as well as exploring the possibility of combining them with other therapeutic agents." (PMID 38571938, 2024). "These proteins have different types of substrates, including cancer-related proteins, such as NOTCH receptor and ligand, epidermal growth factor receptor (EGFR) ligand, interleukin-6 receptor (IL-6R), tumor necrosis factor (TNF) and its receptor, E-cadherin and CD44." (PMID 37370817, 2023). "Finally, HIF-1α and STAT3 can also cooperate to drive cancer cell survival and growth through induction of VEGF, interleukin 6 receptor (IL-6R), HER2, c-Src, PI3K, and JAK/STAT." (PMID 37189677, 2023). "Ligation of IL-6 with IL-6R activates Janus kinase (JAK) tyrosine kinases leading to phosphorylation of signal transducer and activator of transcription 3 (STAT3), which is a well-studied cancer signaling pathway." (PMID 35924148, 2022). "In addition, the results uncovered that the expression of ADAM17 was positively correlated with an immunostimulator (IL6R) and immunoinhibitors (CD274, KDR, TGFBR1) in most cancer types." (PMID 35720350, 2022). "The CD163/IL‐6/Stat3 pathway is suggested to be critical in protumor TAMs, however, macrophage‐mediated cancer cell proliferation was not affected by anti‐IL‐6R antibody (unpublished data)." (PMID 35132816, 2022). "This novel signaling pathway in between fibrogenic PSCs and cancer cells in the TME of PDAC could present a possible therapeutic approach to prevent fibrosis and STAT3 activation through P2X7R inhibition as well as IL-6R neutralization by Tocilizumab." (PMID 34440697, 2021).
cancer (continued). "Recent, some inhibitors of IL-6/STAT3 have been development, such as S31-201 or IL-6 neutralizing monoclonal antibody (IL-6 mAb), Madindoline A (Inhibits the dimerization of IL-6/IL-6R/gpl30 trimeric complexes), C188-9 and Curcumin (Inhibits STAT3 phosphorylation), etc. for treatment of cancers." (PMID 34976809, 2021). "However, the DNA methylation patterns of IL6R and IL6ST receptors has been barely investigated in cancer." (PMID 34576335, 2021). "Epigenetic changes play an important role in the abnormal activation of the IL-6/IL-6R/JAK/STAT3 pathway in cancer, and changes in transcription factor expression and/or activation may be involved in cancer progression." (PMID 33363013, 2020). "miR-21 has been previously shown to target IL6R and PTEN in human cells in the context of cancer." (PMID 32340146, 2020). "IL6 and IL6R also play important roles in the development of several hematological malignancies, including myeloma, B-cell leukemias, lymphomas and non-B cell malignancies." (PMID 32957689, 2020). "Although many evidences confirmed a key role of IL-6 cascades in regulating the growth of malignant cells in preclinical studies, anti-IL6 or anti-IL6R mAbs have not demonstrated clinical efficacy in several cancer types." (PMID 32039001, 2019). "Consequently, IL-6R immunotherapy inhibits the oncogenicity of MCT-1 and cooperates with MCT-1 knockdown to profoundly suppress cancer stemness." (PMID 30885232, 2019). "In addition, MCT-1 elevated the soluble IL-6 receptor levels, and thus, IL-6R antibodies antagonized the effect of MCT-1 on promoting M2-like polarization and cancer cell invasion." (PMID 30885232, 2019). "In the experimental system that is modeled here, the only source of human IL-6 is the cancer cells themselves, as murine IL-6 does not bind to human IL-6R and cannot directly initiate signals on human cells." (PMID 29351275, 2018). "Immunofluorescence staining of IL-6 and IL-6R in GC tissues and adjacent non-cancerous gastric tissues showed that IL-6 was mainly expressed in fibroblasts, while IL-6R in both cancer cells and fibroblasts." (PMID 30158543, 2018). "This enhanced invasion of cancer cells was almost inhibited by the treatment with anti-IL-6R antibody, while the antibody did not affect the cell invasion when no cells were co-cultured." (PMID 25658637, 2015). "Interestingly, IL-6, IL-6R and p-STAT3 were expressed in the residual cancer cells of all the patients in the high expression group with poor response to chemoradiotherapy." (PMID 25761055, 2015). "Furthermore, the expression of p-STAT3 was investigated in the nucleus of the cancer cells, suggesting that STAT3 signaling is activated through autocrine loop stimulation between IL-6 and IL-6R in OSCC cells." (PMID 25761055, 2015). "Moreover, it was shown that when MDSCs were exposed to conditioned media of metastasizing cancer cells, MDSCs secreted exaggerated IL-6 and soluble IL-6Rα, which induced persistent activation of STAT3 in cancer cells." (PMID 24021059, 2013). "Because IL-6 is an upstream target of STAT3 and elevated IL-6 levels in cancer patients have prognostic significance regardless of the cancer type, several compounds targeting IL-6 or IL-6R have been developed and are used for both non-malignant and malignant diseases." (PMID 38339245, 2024). "ENST00000311534 was significantly correlated with HMGB1, ENST00000326094 was significantly correlated with BTN3A1, CD160, TGFBR1, and IL6R, and ENST00000375991 was significantly correlated with CD276, ENTPD1, HMGB1, TLR4, KDR, and TGFBR1 among these 33 immune genes in more than 20 cancer types." (PMID 39766805, 2024). "Therefore, the present study investigated whether blocking IL-6/IL-6R/STAT-3 signaling disrupts proliferation, migration, invasion and clonogenicity of PCa cells; these processes are essential to metastasis in cancer." (PMID 35703345, 2022).
cancer (continued). "Due to the role of STAT-3 in cancer initiation and development, multiple treatments aim to inhibit the IL-6/IL-6R/STAT-3 signaling pathway, one of these treatments is tocilizumab (Tcz), a humanized monoclonal antibody that binds to membrane-bound and soluble IL-6R to inhibit IL-6 signaling." (PMID 35703345, 2022). "Conversely, adding neutralizing antibody either targeting IL-6 or IL-6R could efficiently block the induction of LRG1 mediated by CAFs, supporting that IL-6 was the essential effector derived from CAFs to promote LRG1 expression in cancer cells." (PMID 34930899, 2021). "Considering that the IL-6R/JAK/STAT3 pathway is aberrantly hyperactivated in >70% of cancers, it would be interesting to determine if impairing the palmitoylation of STAT3 with the use of phytochemicals would prove to be successful in hampering cancer cell growth." (PMID 32731620, 2020). "Furthermore, pro‐inflammatory IL‐6 which has been reported to be a critical modulator of cancer progression was significantly upregulated in the miR‐223‐high group, whereas the IL‐6R level was not different between miR‐223‐high and miR‐223‐low groups." (PMID 32491253, 2020). "However, the deferential role of MAO-A and IL-6R in cancer invasion/angiogenesis was not demonstrated previously." (PMID 29695771, 2018). "Therefore, IL-6R overexpression, coupled with enhanced IL-6/STAT3 signaling may facilitate the malignant transformation of EBV-infected premalignant NPE cells into cancer cells, and enhance malignant properties of NPC cells." (PMID 23658720, 2013). "However, recent reports highlighted the intimate involvement between cancer progression and IL-6 trans-signaling through sIL-6R, rather than the classical IL-6 signalling pathway through IL-6R." (PMID 20823887, 2010). "However, when performing GO enrichment analysis for biological processes with the 161 upregulated genes in tumors from mice that received IL-6R blockade compared with those from untreated mice, we found 193 GO terms, 49 of which were not related to cancer immunotherapy." (PMID 39653766, 2025). "Due to the capacity of Hyper-IL6, a fusion protein between IL6 and IL6Rα, to activate gp130 receptors independently of the presence of the ligand-binding IL6Rα subunit, these observations suggest that cancer-initiating cells may not always express sufficient IL6Rα subunits to respond to IL6." (PMID 20478049, 2010). "We did not observe any significant difference in STAT3 expression and less expression of IL6R and IL6ST in cancer samples compared to paired non-neoplastic samples." (PMID 38979413, 2024). "It is important to consider that there are other activators of JAK/STAT3 pathway besides IL-6, and only individual nodes of the target, including IL-6 and IL-6R, are targeted by FDA approved agents, not necessarily in the context of cancer." (PMID 38313431, 2023). "Our results demonstrate that IL-6R protein expression on plasma membrane of PA-1 and SKOV-3 cancer cells but not in cytosol predicts responsiveness to ascites in cell-based models of EOC invasion (Figure 5E1-2)." (PMID 27825119, 2016). "Although evidence of direct interaction between ERBA and IL-6/IL-6R is lacking, ERBA specifically suppressed IL-6 activities and alleviated cancer cachexia." (PMID 26840088, 2016). "0This study analyzed IL6R expression on a large cohort of CRC patients; we found a significantly lower expression in the cancer group and a non-significantly higher expression in the metastatic group compared to primary cancer and a slightly lower expression in the KRAS-positive group." (PMID 37869102, 2023).
infection (92 papers, 2010 to 2025). The state of being infected such as from the introduction of a foreign agent such as serum, vaccine, antigenic substance or organism. "The majority of large observational studies for infection risk and IL6R blockade stems from studies of tocilizumab, the first IL6R antagonist approved for use in the US for RA." (PMID 38580710, 2024). "In contrast, functional IL6R blockade appears to show evidence suggesting increases in susceptibility to infections, matching trial and registry data." (PMID 36716318, 2023). "Of these, interleukin-6 receptor inhibitors, used only in RA, pose a higher risk of serious infection than tumor necrosis factor inhibitors, commonly used throughout all IMIDs." (PMID 37409280, 2023). "Among the possible complications of anti-IL-6R is the increased susceptibility to infection and reduced generation of Th17 cells." (PMID 29386580, 2018). "Here, IL-6R blockade halved the loss of weight in Ifitm3–/– mice seen during the first 4 days of infection." (PMID 28240600, 2017). "We explored the hypothesis that anti-inflammatory intervention via interleukin 6 receptor (IL-6R) blockade would influence plasma lipid levels during severe infection and evaluated the association of plasma lipid changes with clinical outcomes." (PMID 38795859, 2024). "Although in vitro work has confirmed that this variant reduces cell surface expression of IL6R and large-scale transcriptome studies in healthy patients and those with infection have shown this is a splicing variant, the use of a single variant reduces the statistical power of the study." (PMID 36801374, 2023). "The objective of the present study was to ascertain whether changes in iron metabolism induced by anti-IL-6R biologic therapy were associated with an increased risk of infection." (PMID 31261772, 2019). "The objective of the present study was to ascertain whether changes in iron metabolism induced by anti-IL-6R biologic therapy were independently associated with an increased infection risk." (PMID 31261772, 2019). "This was a prospective longitudinal pilot study designed to evaluate whether changes in iron metabolism induced by anti-IL-6R biologic therapy were independently associated with an increased risk of infection in patients with RA." (PMID 31261772, 2019). "It was recently reported that IL-6Rα-deficient mice show increased resistance to P. chabaudi infection and that IL-6 trans-signaling, but not IL-6 classic signaling, contributes to a lethal outcome of infection." (PMID 26991425, 2016). "Certainly, mutations in other immune genes such as S100A15 or IL6R also have the potential to play a role in severity and chronicity of infection and modulation of the immune response to various pathogens, as do non-coding mutations that may be impacting gene regulatory elements." (PMID 35157719, 2022). "The shedding of IL-6R in infected macrophages was measures at 11,525 ± 1986 pg/mL (24-hour infection), and 12,497 ± 122.7 pg/mL (48-hour infection) compared to 10,300 ± 321.3 pg/mL in uninfected macrophages (P-value < 0.05)." (PMID 39170608, 2024). "IL6R simulates the movement of T cells and other immune cells to the site of infection or inflammation and affects T cell and B cell differentiation." (PMID 37503080, 2024). "According to the current consensus, immunosuppressants (e.g., steroids, tocilizumab, and anti-interleukin-6 receptor monoclonal antibodies) play an important role in the early stages of infection." (PMID 35448570, 2022). "According to the current consensus, immunosuppressants, such as dexamethasone and anti-interleukin-6 receptor monoclonal antibodies, are therapeutic medications in the early stages of infection." (PMID 35448570, 2022). "In this study, yellow catfish il-6rα and il-6rβ mRNAs were significantly up-regulated from 3 h or 12 h to 120 h post-infection." (PMID 33732247, 2021).